H19 (H19 imprinted maternally expressed transcript)
Diseases named in the same sentence as H19 in open-access papers (continued):
Sharing a sentence is not in itself a finding about the gene and the disease.
type 2 diabetes (17 papers, 2016 to 2025). "Numerous illnesses, including cancer, type 2 diabetes, and hypertrophic cardiomyopathy, are linked to the abnormal expression of H19." (PMID 36428545, 2022). "Genetic variance in the H19 gene is related to the risk of type 2 diabetes with bioinformatics suggesting that the relevant polymorphisms would affect H19-miRNA interactions." (PMID 31590432, 2019). "In contrast with the decreased H19 levels in the retinal tissues or the vitreous humor, circulating H19 was found up-regulated in patients with type 2 diabetes compared with healthy controls." (PMID 35946958, 2022). "H19 is notably upregulated in all the listed age-related diseases in which inflammation plays a crucial role except Type II diabetes." (PMID 33193379, 2020). "H19 is significantly decreased in the muscle of humans with type-2 diabetes and insulin-resistant rodents, and this decrease is correlated with increased let-7 bioavailability." (PMID 33071823, 2020). "In humans, the abundance of H19 was significantly decreased in the skeletal muscle of subjects with type 2 diabetes." (PMID 31590432, 2019). "This suggests that circulating H19 can be used as an additional biomarker for type 2 diabetes." (PMID 35946958, 2022). "Both the levels of H19 in fetuses with maternal diabetes and skeletal muscle of type 2 diabetes(T2D) patients decreased strongly." (PMID 33193379, 2020). "A close correlation between circulating H19, HOTAIR, MIAT and SENCR levels was also observed in the type 2 diabetes group." (PMID 27874027, 2016). "Similarly, the NCT04767750 trial has been completed, with the objective of exploring the role of lncRNA H19 in the regulation of IGF-1R expression and investigating the mechanistic links between HCC and type 2 diabetes mellitus (T2DM)." (PMID 39827195, 2025).
esophageal cancer (16 papers, 2013 to 2025). A primary or metastatic malignant neoplasm involving the esophagus. "The molecular mechanisms via which HNF1A-AS1 regulates esophageal cancer include the regulation of H19 expression and effects on the nucleosome and chromatin assembly pathways." (PMID 35241975, 2022). "This demonstrates that H19 mediates the malignant progression of esophageal cancer via the STAT3/EZH2/β-catenin axis in vivo and in vitro." (PMID 35241975, 2022). "In esophageal cancer cells, elevated let-7c expression following knocking down of lncRNA H19 is reported to repress cell proliferation, migration, invasion as well as EMT and metastasis via inhibition of the STAT3-EZH2-β-catenin pathway." (PMID 34572067, 2021). "First, we removed lncRNAs with longer than 4000 nucleotides and then eliminated the molecules that have already been studied in esophageal cancer such as H19, SNHG6, LUCAT1, HOXA11." (PMID 34659577, 2021). "The oncogenic potential of lncRNA H19 was demonstrated in different tumor types (e.g., liver and esophageal cancer) and overexpression of lncRNA H19 was observed in parallel with upregulation of the membrane glycoprotein p95 in multidrug-resistant tumors." (PMID 29967761, 2018). "High expression of H19 promoted the proliferation and invasion of esophageal cancer cell lines, whereas the opposing effects were observed by H19 knockdown." (PMID 27738631, 2016). "H19 promoted esophageal cancer cell metastasis via negatively regulating let-7c, an anti-EMT miRNA." (PMID 38948025, 2024). "The resulting signatures include genes that are highly related to cancer, such as H19 and NEAT1, which possess perfect prognostic values for esophageal cancer and HNSCC, respectively." (PMID 32024523, 2020). "In esophageal cancer cells, elevated H19 expression promotes EMT and metastasis through activation of the STAT3/EZH2/β-catenin axis, and, interestingly, H19 was directly targeted by let-7c, suggesting a mutual negative-feedback regulation between H19 and let-7c." (PMID 34572067, 2021).
male infertility (16 papers, 2013 to 2025). The inability of the male to effect fertilization of an ovum after a specified period of unprotected intercourse. "In male infertility, hypomethylation of H19 is associated with conditions such as oligozoospermia and asthenozoospermia." (PMID 39311136, 2024). "A recent meta-analysis has confirmed this association between male infertility and aberrant sperm DNA methylation, in particular for imprinted regions H19, MEST, and SNRPN." (PMID 31462300, 2019). "Importantly though, a number of studies have reported an association between male infertility and aberrant sperm DNA methylation for the genomic imprinted regions H19, MEST, and SNRPN." (PMID 31462300, 2019). "Despite the heterogeneity among the studies, MEST and H19 have become the most prominent candidates for evaluating male infertility." (PMID 39017772, 2024). "Recent meta-analyses focusing on MEST and H19 indicated that methylation studies in male infertility reveal diverse results due to the heterogeneity among the studies." (PMID 39017772, 2024). "Given the critical role of H19 in in vitro fertilization (IVF) and male infertility, we examined the imprinting status of the H19/IGF2 cluster in decidual tissues." (PMID 36231092, 2022). "Our data further supports the need for Dnmt3a2 expression during spermatogenesis, suggesting an active role for Dnmt3a2 at completing the methylation of multiple genomic regions in sperm, more importantly in imprinted genes related to male infertility, such as H19." (PMID 40630543, 2025). "The methylation profiles of CpG sites within the ICR of imprinted genes H19 and small nuclear ribonucleoprotein polypeptide N could be used as epigenetic biomarkers to evaluate male infertility with multiple sperm defects." (PMID 37507391, 2023). "H19 and MEST were the most investigated genes in aberrant sperm samples, showing repetitively aberrant loss or gain of methylation, respectively, which, in turn, may be causal factors in the development of male infertility." (PMID 34368137, 2021). "An abnormal DNA methylation status of specific genes such as MEST (mesoderm-specific transcript), H19 (H19 imprinted gene), and MTHFR (methylenetetrahydrofolate reductase) is connected to male infertility." (PMID 36834790, 2023). "Studies have shown that the methylation level of the H19 ICR in men with oligozoospermia and asthenospermia is significantly lower than that in healthy men, suggesting a connection between the hypomethylation of the H19 ICR and male infertility." (PMID 37507391, 2023). "We examined methylation of the ICRs of H19, MEST, KCNQ1OT1 and SNRPN, genes previously reported to be altered in male infertility and/or regions known to have roles in imprinting disorders." (PMID 36611168, 2023). "Methylation anomalies of the H19, IGF2, GNAS, GNASAS, and MEST imprinted genes have not previously been associated with male infertility based on transcriptome data." (PMID 39017772, 2024). "Particularly, DNA methylation defects of MEST and H19 within imprinted genes and MTHFR within non-imprinted genes have been repeatedly linked with male infertility." (PMID 34368137, 2021).
pituitary tumor (16 papers, 2018 to 2025). A benign or malignant neoplasm affecting the pituitary gland. "First, we showed that H19 was downregulated in human pituitary tumour tissues, which was associated with poor progression of pituitary tumourigenesis." (PMID 30397197, 2018). "Given that H19 expression was downregulated in pituitary tumours and its decreased expression was associated with pituitary tumour progression, we speculated that increasing H19 expression may suppress the growth or initiation of pituitary tumours." (PMID 30397197, 2018). "In additon, the expression level of exosomal H19 in the plasma of human patients with all subtypes of pituitary tumors was significantly lower than that in the healthy subjects." (PMID 35563510, 2022). "In the pituitary tumor context, H19 directly binds with 4E-BP1 and competitively inhibits it binding to the key energy sensing protein mTORC1, resulting in reduced 4E-BP1 signaling." (PMID 32266130, 2020). "Significantly, over expression of H19 was more effective than the dopamine agonist cabergoline, the first-line treatment for pituitary tumors, at inhibiting tumor cell growth in in vivo models." (PMID 32266130, 2020). "To compare the effect between CAB and H19 overexpression on pituitary tumour growth, we performed xenograft experiments and found that H19 overexpression was more potent in suppressing tumour growth than CAB." (PMID 30397197, 2018). "To further investigate the function of H19 in pituitary tumour cells, we stably knocked down H19 expression using lentiviral small hairpin RNAs (shRNAs) in GH3 cells." (PMID 30397197, 2018). "Collectively, these data indicate that H19 suppresses pituitary tumour cell proliferation and tumour growth by blocking 4E-BP1 phosphorylation and function." (PMID 30397197, 2018). "Collectively, these results show that H19 overexpression can inhibit pituitary tumour proliferation in vitro and in vivo." (PMID 30397197, 2018). "We found that the H19 expression level was significantly downregulated in the prolactinomas and the other pituitary tumour subtypes compared with that in the normal pituitary glands." (PMID 30397197, 2018). "Consistently, upregulation of H19 expression inhibits pituitary tumour cell proliferation in vitro and tumour growth in vivo." (PMID 30397197, 2018). "The same authors have noted in a previous study that the expression of lncRNA H19 is decreased in pituitary adenomas (PAs), and H19 overexpression could markedly inhibit the proliferation of pituitary tumor cells." (PMID 40362297, 2025). "H19 overexpression inhibited contralateral pituitary tumor growth in vivo." (PMID 35563510, 2022). "On the other hand, long ncRNA H19 was found to inhibit mTORC1 in pituitary tumors." (PMID 36203751, 2022). "In this study, we aimed to determine the potential role of H19 in pituitary tumour progression." (PMID 30397197, 2018). "First, we found that H19 expression was significantly reduced in pituitary tumours." (PMID 30397197, 2018). "Moreover, we transfected wild-type or an 4E-BP1-binding-deficient mutant H19 into H19 knockdown GH3 cells or normal GH3 cells to confirm that the interaction between H19 and 4E-BP1 indeed plays a critical role for pituitary tumour cell proliferation." (PMID 30397197, 2018). "Taken together, these results indicate that 4E-BP1 might be the key target of H19 in regulating pituitary tumour growth by inhibiting 4E-BP1 phosphorylation and subsequent protein synthesis." (PMID 30397197, 2018). "Finally, we demonstrate that H19 is more effective than cabergoline treatment in the suppression of pituitary tumours." (PMID 30397197, 2018). "Taken together, these results suggest that H19 effectively inhibits primary prolactinoma progression by inhibiting 4E-BP1 phosphorylation and that increasing H19 expression may serve as a potential therapeutic strategy for pituitary tumours." (PMID 30397197, 2018).
pituitary tumor (continued). "To further test whether the H19-mediated cell growth inhibition is physiologically important, we constructed a rat prolactinoma pituitary tumour in situ model by administering oestrogen to Fischer 344 rats." (PMID 30397197, 2018). "Together, our study uncovered the role of H19-mTOR-4E-BP1 axis in pituitary tumour growth regulation that may be a potential therapeutic target for human pituitary tumours." (PMID 30397197, 2018). "Since our study demonstrates that H19 is a tumour suppressor in pituitary tumours, it would be interesting to know whether H19 acts similarly in other tumours where H19 is a tumour suppressor." (PMID 30397197, 2018). "Furthermore, we revealed that H19 acted as a tumour suppressor, inhibiting pituitary tumour growth by negatively regulating 4E-BP1 phosphorylation." (PMID 30397197, 2018). "However, papers concerning H19 and pituitary tumours are limited." (PMID 37189829, 2023). "Interestingly, mTOR was also found to be regulated by lncRNA H19 in pituitary tumors." (PMID 36203751, 2022). "Thus, CAB may have a synergistic effect with H19 overexpression in the inhibition of pituitary tumour growth." (PMID 30397197, 2018). "In addition, H19 bound to 4E-BP1 in primary pituitary tumour cells." (PMID 30397197, 2018). "LncRNA H19 suppresses mTORC1 function and blocks mTORC1-mediated phosphorylation of 4E-BP1 to inhibit pituitary tumor cell proliferation in vitro and in vivo." (PMID 37313458, 2023). "In our study, H19-mediated inhibition of 4E-BP1 phosphorylation resulted in translation stagnation and pituitary tumour growth arrest in vivo." (PMID 30397197, 2018). "To test this idea, we stably expressed H19 in pituitary tumour GH3 cells and found that H19 overexpression strongly inhibited GH3 cell proliferation." (PMID 30397197, 2018). "Interestingly, H19 interacts with 4E-BP1 at the TOS motif and inhibits 4E-BP1 binding to Raptor competitively, implying that inhibition of pituitary tumors by H19 is more effective compared with carte blanche treatment." (PMID 34081618, 2021). "Given the specific effect of H19 on 4E-BP1 phosphorylation, we examined whether 4E-BP1 may directly mediate the H19 effect on the suppression of pituitary tumour cell proliferation and growth." (PMID 30397197, 2018). "Additionally, the suppressive influence of H19 on tumour cell proliferation and the negative correlation between H19 and pituitary tumour volume has been shown." (PMID 37189829, 2023). "Therefore, the H19–4E-BP1 axis and the CAB–AKT/mTOR axis may be of great therapeutic potential for targeting human pituitary tumours that are refractory to available therapies or surgical treatment." (PMID 30397197, 2018).
heart failure (15 papers, 2017 to 2025). Inability of the heart to pump blood at an adequate rate to meet tissue metabolic requirements. "Aged H19 deficient mice show increased fibrosis, expression of markers indicative of cardiac failure, abnormal echocardiography phenotypes, low blood pressure, and aberrant vasculature." (PMID 34402430, 2021). "In heart failure, H19 is reported to be upregulated in a transverse aortic constriction model, and it inhibits cardiomyocyte hypertrophy by encoding miR-675, which targets CaMKIIδ." (PMID 35990951, 2022). "In failing hearts of mice, pigs and humans, expression of the lncRNA H19 was reduced and an H19 vector–based, cardiomyocyte-directed gene therapy was able to attenuate heart failure." (PMID 34791525, 2022). "The H19 gene therapy prevents and reverses experimental pressure-overload-induced heart failure according to interaction with the polycomb repressive complex 2, suppressing H3K27 trimethylation, which, in turn, leads to reduced NFAT expression and activity." (PMID 35990977, 2022). "lncRNA H19 (H19), a well-known long noncoding RNA (lncRNA), is involved in the pathophysiological process of multiple cardiovascular disease such as heart failure, cardiac ischemia and fibrosis." (PMID 33664669, 2021). "Contrary to that, another line of data finds a low expression of H19 in heart failure mice." (PMID 35990951, 2022). "In pathological HCM and heart failure tissues, H19 and its host miR-675 were upregulated." (PMID 34502285, 2021). "In pathological heart failure and cardiac hypertrophy, H19 and its host miR-675 are upregulated." (PMID 34502285, 2021). "Furthermore, loss-of-function and gain-of-function models were utilized to determine the functional role of H19 in heart failure progression." (PMID 31588235, 2019). "We noticed the re-expression of lncRNA H19 was only observed in the MI-induced heart failure model suggesting that the depletion of oxygen in the MI model might promote lncRNA H19 expression." (PMID 31588235, 2019). "To determine whether H19 upregulation in HLHS hearts is a general consequence of heart failure, we assessed cardiac H19 expression in patients with heart failure due to aortic stenosis, hypertrophic obstructive cardiomyopathy (HOCM), and non-ischemic dilated cardiomyopathy (DCM)." (PMID 41446187, 2025). "Further studies identified that plasma levels of H19 and LIPCAR were also increased in CAD patients with heart failure compared to those with normal cardiac function." (PMID 28790415, 2017).
osteoarthritis (15 papers, 2013 to 2023). A noninflammatory degenerative joint disease occurring chiefly in older persons, characterized by degeneration of the articular cartilage, hypertrophy of bone at the margins and changes in the synovial membrane. "Peripheral blood of osteoarthritis patients had an increased expression of lncRNA H19, which was linked to the occurrence and development of osteoarthritis." (PMID 37779916, 2023). "Apart from these functions, H19 is also implicated in several other physiological conditions or diseases, such as cartilage degeneration in osteoarthritis, skeletal muscle differentiation and regeneration, and glucose metabolism in muscle cells." (PMID 29636074, 2018). "In addition, lncRNA H19 gene polymorphisms were associated with risk of osteoarthritis in a Chinese Han population." (PMID 37779916, 2023). "For example, the lncRNA H19 could regulate osteogenesis by sponging miR-675 and associating with cartilage regeneration, and abnormal H19 expression was found in patients with osteoarthritis." (PMID 33006314, 2020). "Exosomal lncRNA H19 regulated the progression of osteoarthritis via governing the miR-106b-5p/TIMP2 axis." (PMID 37779916, 2023). "Umbilical cord blood MSCs produced lncRNA H19 controlled central sensitization of pain via targeting miR-29a-3p/FOS pathway in osteoarthritis." (PMID 37779916, 2023). "For example, depletion of lncRNA H19 reduced LPS-mediated damage via regulation of miR-130a in osteoarthritis." (PMID 37779916, 2023). "LncRNA H19 regulated cartilage matrix degradation and calcification via interaction with miR-140–5p in osteoarthritis." (PMID 37779916, 2023). "Overexpression of lncRNA H19 enhanced apoptosis and decreased the proliferation in IL-1β-mediated chondrocytes via sponging miR-106a-5p in osteoarthritis." (PMID 37779916, 2023). "Similar findings for the interaction between H19 and miR-140-5p were found in osteoarthritis and bone formation." (PMID 35198556, 2022). "Recently, the level of H19 was discovered to become substantially enhanced in osteoarthritis tissues, indicating a prospective role of H19 in the progression of inflammatory conditions." (PMID 34630738, 2021). "On the other hand, H19 is significantly upregulated in patients with osteoarthritis, whereas, its expression is suppressed by TNF-α and IL-1β." (PMID 33193379, 2020). "Comparing RA synovial tissue to osteoarthritis and normal/joint trauma controls revealed a higher expression of H19 transcripts both in situ and by semi-quantitative PCR." (PMID 23429271, 2013). "Several studies have demonstrated that lncRNA H19 regulates osteoarthritis progression." (PMID 37779916, 2023). "Analysis of synovial specimens (macrophages and fibroblasts) isolated from 26 patients with RA, 25 patients with osteoarthritis, and 2 patients with reactive arthritis compared with 15 control samples showed significant overexpression of the lincRNA H19 in the RA samples and osteoarthritis samples." (PMID 35796900, 2022). "Thus, H19 might directly participate in the development of osteoarthritis (OA) though the TGF-β pathway." (PMID 33193379, 2020).